CUL3 (cullin 3)
Diseases named in the same sentence as CUL3 in open-access papers (continued):
Sharing a sentence is not in itself a finding about the gene and the disease.
tumor (63 papers, 2012 to 2026). "A previous study demonstrated that anti-PD-L1 treatment combined with sorafenib efficiently inhibits tumor progression in Cul3-deficient tumors." (PMID 38212325, 2024). "Conclusively, CUL3 was found to be associated with cell cycle progression, and DNA damage response, exhibiting diverse roles depending on the tumor's molecular type." (PMID 38942922, 2024). "Suppressing Cul3 expression was also sufficient to reduce the growth of GB model tumours in vivo, whereas NF1 null cells were unaffected by loss of Cul3." (PMID 33432111, 2021). "Tumor cells effectively maintain the intracellular antioxidant state through Nrf2 activation as a result of mutations in genes such as NRF2, KEAP1, and CUL3, which accelerate tumor cell growth and contribute to the development of resistance to anti-tumor drugs." (PMID 40544155, 2025). "Additionally, mutations in CUL3 or NFE2L2 are present in about 1% of ccRCC tumours according to TCGA data." (PMID 39707614, 2025). "While CUL3 mutations may compromise its tumor-suppressor function and promote progression, the roles of HMCN1 and TBX3 are less defined." (PMID 41479892, 2025). "The Cul3 mutation appears to induce immune environment changes that contribute to tumor formation." (PMID 38212325, 2024). "Mutations in CUL3 and abnormalities in its expression may result in either oncogenic or tumor suppressive processes and could be possible target for treatment strategies." (PMID 35409691, 2022). "We observed Brd4, Cul3, and Trip12 to be commonly mutated genes across different tumor types, suggesting that there may be common mechanisms perturbed by the Onc2.3 transposon to drive tumorigenesis in the absence of oncogenic events." (PMID 33435458, 2021). "The present study demonstrated that the KEAP1/NFE2L2/CUL3 mutations might be correlated to the lower immune infiltration and higher tumor mutation burden." (PMID 34617407, 2021). "The remarkably increased levels of these cytokines induced by Cul3 deficiency could attract CD8 T cells to tumor cells and explained their accumulation in the liver." (PMID 34803491, 2021). "These analogs selectively decline CUL1 and CUL3 neddylation levels, demonstrating the potential for anti-tumor activity." (PMID 41540013, 2026). "Among them, compound 27 exhibits 25-fold greater potency than the initial hit, effectively stabilizing DCN1 and specifically decreasing the CUL1 and CUL3 neddylation levels in tumor cells." (PMID 41540013, 2026). "WES analysis of 60 pRCC specimens revealed six tumours (10%) with mutations in the four key genes, NFE2L2, KEAP1, CUL3 and BACH1, of the NRF2‐ARE pathway." (PMID 39707614, 2025). "Mutations of ARID2, CUL3, TET1, FBXW7, EZR and GPHN were frequently accompanied by copy number loss consistent with their predicted/documented tumour suppressor roles." (PMID 38106039, 2023). "Eventually, these outcomes demonstrate that COX-2/exo-miR-1290 pathway promotes CAFs activation and tumor progression by decreasing CUL3 expression in fibroblasts." (PMID 37723559, 2023). "Specifically, COX-2/exo-miR-1290/CUL3 is suggested as a novel signaling pathway for mediating CAFs activation and tumor progression in LUAD." (PMID 37723559, 2023). "The GSEA results manifested that KEAP1/NFE2L2/CUL3 Mut group patients have a complex ROS mechanism that affects tumor development." (PMID 34617407, 2021). "RBM47 suppresses Nrf2 activity by upregulating KEAP1 and CUL3, and suppressing some Nrf2 activators, leading to the inhibition of tumor growth in vivo." (PMID 34804951, 2021).
tumor (continued). "When pathway analysis was carried out, alterations in those linked to oxidative stress were found in 22% of tumours due to mutations in KEAP1 (mutated in 19%), CUL3 (mutated in >1%) and NFE2L2 (mutated in 3%)." (PMID 33276631, 2020). "Mutations in KEAP1 and CUL3 genes are mutually exclusive with the one in the NFE2L2 gene present in 6.6% of ccRCCs; indeed 10.4% of the tumor analyzed presented a deletion in the CUL3 locus 2q36." (PMID 33233657, 2020). "SPOP is a tumor suppressor protein and substrate adaptor of the cullin 3-RING-ubiquitin ligase (CUL3); tumor-associated SPOP mutations disrupt substrate binding and ubiquitination, leading to increased expression of oncogenic substrates." (PMID 31366128, 2019). "circ_000334, circ_006740, and circ_006371 are spliced from spermatogenesis-associated protein 6 (SPATA6), CUL3, and SLC38A1, which play an important role in tumor proliferation, migration, and apoptosis." (PMID 30349810, 2018). "A significant number of recent studies shed light on the biological functions of Cul3 E3 ligases that regulate tumor development, progression, and therapeutic response." (PMID 27200299, 2016). "Our analysis on individual complex component genes revealed that, in addition to different frequencies of disruption, each tumor type displays a distinctive pattern of CUL3/KEAP1/RBX1 E3-ubiquitin ligase complex alterations." (PMID 25114896, 2014). "Nrf2 activity was found suppressed in tumor cells due to increased expression of the ubiquitin ligase Cul3 that, together with Keap1, targets Nrf2 for degradation by the proteasome." (PMID 24491031, 2014). "Intriguingly, a recent study demonstrated that a protein, cullin-3, prevented HpSCs from becoming tumor-initiating cells." (PMID 23192764, 2013). "To identify additional drivers that accelerate ICC formation, we previously performed CRISPR/Cas9-mediated genome-wide screening targeting 20,611 genes in SPC mice and identified Cul3 as a tumor suppressor, whose disruption accelerated ICC formation by inducing inflammation in the liver." (PMID 38212325, 2024). "Notably, Speckle-type POZ protein (SPOP) serves as a tumor suppressor through its function as a substrate receptor for Cullin 3 (CUL3)-based ubiquitin ligases and mediates ubiquitination and degradation of PD-L1." (PMID 38340178, 2024). "Consequently, we found that COX-2-mediated exo-miR-1290 improves CAFs activation and tumor progression by suppressing CUL3 expression and upregulating Nrf2 expression and Nrf2-mediated FAP-1 and FN1 transcription in fibroblasts." (PMID 37723559, 2023). "However, we corroborated the tumor-suppressive roles of insertions in Adk and Zbtb20 and in Nipbl, Pdlim5, Ppp1r12a, Tnrc6b, Brd4, Cul3, Ctnna3, Elavl1, Gphn, Nfia, Ptpn12, Taok3, and Rasa1." (PMID 33435458, 2021). "The progression‐free survival (PFS) analysis, which can better reflect tumor progression and predict clinical benefits, also showed an association between KEAP1/NFE2L2/CUL3 mutation and faster disease progression (median survival time: 17.7 months vs. 31.7 months, p = 0.016)." (PMID 34617407, 2021). "SPOP is an adaptor protein of Cullin 3-based E3 ubiquitin complexes, has been shown to participate in diverse cellular processes and plays tumor suppressive roles in PrCa, suggesting that HnRNPK may be a substrate of SPOP." (PMID 34857003, 2021). "We also recount events that led to the recognition that NRF2 is frequently upregulated in tumour cells, and describe a wide range of mechanisms that allow it to escape repression by KEAP1, with somatic mutations in NFE2L2, KEAP1 and CUL3 being the best characterized examples." (PMID 33276631, 2020). "Noteworthy, also in dSSc samples, we observed the down-modulation of the tumor suppressor CUL3." (PMID 29559981, 2018). "Thus, PPI network analysis suggested that the cross-talk of KEAP1, NRF2, and CUL3 with the 17-gene signature coordinately drives tumor progression and therapeutic resistance in HNSCC." (PMID 29306329, 2018).
tumor (continued). "However, unlike the other four genes, the Cul3 mutation did not accelerate ICC cell proliferation but instead interfered with the tumor immune microenvironment." (PMID 38212325, 2024). "These investigations about immune infiltration and tumor environment indicated that the Wild group patients might have a higher immunotherapy response rate due to the TME status and the KEAP1/NFE2L2/CUL3 alterations that contribute to the tumor immune escape and “cold” tumor's formation." (PMID 34617407, 2021). "Notably, mutations in NFE2L2, KEAP1 and CUL3 that cause persistent upregulation of NRF2 often co-exist with mutations that activate KRAS and the PI3K-PKB/Akt pathway, suggesting NRF2 supports growth of tumours in which KRAS or PKB/Akt are hyperactive." (PMID 33276631, 2020). "Similar to previous results, the Cul3 knockout recruited more immune cells, including CD3+ T cells and F4/80+ macrophages, to the tumor." (PMID 38212325, 2024). "Further investigation revealed that lactate derived from CAFs negatively regulates the HIPPO pathway through the DLG5/CUL3/MST1 axis, thus promoting the nuclear localization of YAP1 and enhancing the tumor stem cell phenotype." (PMID 39605072, 2024). "The E3 ubiquitin-protein ligase, CUL3, inhibits autophagy by mediating the ubiquitination and degradation of BECN1, thereby promoting tumor occurrence and development." (PMID 36611207, 2023). "It was found that TERT‐induced miR500A mediated the down‐regulation of PTCH1, GLI3 and CUL3, while miR500A directly targets the 3′UTR of PTCH1, promoting tumour invasiveness." (PMID 33713376, 2021). "Using GO biological process enrichment analysis, we found that CUL1, CUL3, RNF2, and RPA2 overlap in their mitotic cell cycles, which has important biological implications in tumor development." (PMID 32170141, 2020). "ABCG2, Cul3, IGFBPR5, PTEN, and SPARC genes levels of expression were related to the malignant phenotype in tumor cells, and those differential expressions were found to be modulated by Maitake in our previous studies." (PMID 27401257, 2016). "We evaluated the frequency of CUL3, RBX1, and KEAP1 disruption across multiple tumor types from the TCGA, selected based on data availability from TCGA (Section 2)." (PMID 25114896, 2014). "Furthermore, Cullin3 (CUL3), a potential target of miR-1290, was found to suppress COX-2/exo-miR-1290-mediated CAFs activation and ECM production, consequently impeding tumor progression." (PMID 37723559, 2023). "Acting as an adapter that bridges the E3-ligase CUL3 and the substrate DDX3X, KLHL29 executes the tumor suppressive function by enhancing the proteasomal degradation of DDX3X, consequently leading to the downregulation of cyclins and cell cycle arrest at G0/G1 phase." (PMID 37845393, 2023). "In our third patient, the primary tumor showed a combination of TSC1, CUL3, DOT1L and SETD2 gene mutations (but not BAP1), whereas the PM had the same genetic mutations plus BAP1 mutation." (PMID 34885018, 2021). "In the patient without VHL mutation, we found alterations in CUL3, DOT1L, SETD2 and TSC1 in the primary tumor, with the addition of BAP1 gene mutation in its analyzable PMs." (PMID 34885018, 2021). "Despite activating hotspots in NFE2L2 and inactivating mutations in its negative regulators, KEAP1, CUL3, and SIRT1 have been reported, they do not justify themselves the overexpression of NRF2 transcriptional signature in the different tumor types." (PMID 33233657, 2020). "Moreover, in human tumor biopsies, IKKβ protein levels are inversely correlated with KEAP1/CUL3 levels." (PMID 26301506, 2015).
tumor (continued). "Taken together, the potential implications of DNA-level alterations affecting components of the CUL3/KEAP1/RBX1 protein complex are broad and, cumulatively, may have profound implications in tumor biology." (PMID 25114896, 2014). "Known tumor suppressor genes, e.g., CDKN2A (9p21.3), PTEN (10q23), and RB1 (13q14) were located within HD regions, as well as genes with potential tumor suppressor properties, e.g., CUL3 (2q36.2) and MGMT (10q26)." (PMID 22685613, 2012). "As mutations in NRF2-regulating tumor suppressors KEAP1 and CUL3 are not confined to specific hotspot regions, our findings advocate for a multimodal profiling approach combining somatic mutation assessment with protein or transcriptomic evaluation of NRF2 targets." (PMID 41771797, 2026). "Consequently, the CUL3-Nrf2 pathway may be a new target to overcome CAFs activation and ECM production, and eventually impeding tumor progression in LUAD." (PMID 37723559, 2023). "In order to investigate the effects of COX-2/exo-miR-1290/CUL3 pathway on CAFs activation and tumor progression in vivo, we established tumor xenografts in nude mice by subcutaneously implanting A549-COX-2 cells and NIH-3T3 cells with or without stably expressing CUL3." (PMID 37723559, 2023).
infection (12 papers, 2013 to 2025). The state of being infected such as from the introduction of a foreign agent such as serum, vaccine, antigenic substance or organism. "Compared to that in the control group, Cullin 3 silencing markedly increased the viral titer in the supernatant post-infection." (PMID 40396757, 2025). "This also potentially dampens the overall effect of Cul3 on infection in this experimental setup, as a significant number of cells are efficiently infected without Cul3 being overexpressed." (PMID 32882949, 2020). "In line with previous results, depletion of Cul3 in HEK293T cells increased infection with wild type HIV-1 NL4-3 but also with HIV-1 ∆STAT5 I, II, III, ∆NF-IL6 I, II and ∆USF up to 15-fold." (PMID 32882949, 2020). "Poxvirus BTB–Kelch protein EVM150 has been shown to co-precipitate with Cul3 and modulate innate immune responses upon infection." (PMID 30819806, 2019). "Consistently, simian β-TrCP down-regulation induced by human RV Wa strain infection was counteracted by Cul3 depletion." (PMID 27706223, 2016). "To identify the BTB-domain containing CRL3 substrate-adaptors involved in endosome maturation, we took advantage of the observation that IAV depends on CUL3 activity for cell entry and infection." (PMID 27008177, 2016). "Consistently, loss of either CUL3 or IMMT reduced the colocalization of mitochondria with lysosome upon B. pseudomallei WT infection, while no obvious differences were found when infected with ΔbipD mutant." (PMID 38834545, 2024). "Our data is consistent with previous work as CUL3 has been demonstrated to negatively regulate HIV-1 transcription during productive infection directly or indirectly through the NFκB pathway as NFκB/NFAT binding sites at the LTR are critical for regulating viral transcription." (PMID 36706161, 2023). "Interestingly, we show that inactivation of the Cul3 protein by dominant-negative approach affected viral E1A mRNA and protein accumulation during early phase of infection." (PMID 24260437, 2013). "In addition, we demonstrate the involvement of the functional Cul3 protein in adenovirus E1A gene expression during early phase of the infection." (PMID 24260437, 2013). "Theoretically, the functional Cul3 protein might act directly to achieve an efficient E1A transcription during early phase of infection." (PMID 24260437, 2013). "Moreover, Cullin 3 cleavage induced by EV-D68 infection occurred in a cell type-independent manner." (PMID 40396757, 2025). "At 8 h post-EV-D68 infection, when VP1 was undetectable via western blotting in the control group, VP1 protein expression was detectable in the Cullin 3-knockdown group." (PMID 40396757, 2025). "As expected, knockout of CXCR4 drastically decreased the number of HIV-1 infected cells compared to the NT control, whereas Cul3 knockout correlated with a robust increase of HIV-1 infected cells, as measured by flow cytometry 72 h post infection." (PMID 32882949, 2020). "In addition to revealing the TRAF-2 and TRAF-6 ubiquitin ligase complexes, which have known roles in immune signaling during infection, this analysis identified ubiquitin ligase complexes, including CUL3, RBX1, and MDM2, that have not been previously implicated in Mtb pathogenesis." (PMID 31951200, 2020). "Nevertheless, the mRNA level of Immt showed no significant changes no matter when Cul3, Klhl9 or Klhl13 was knocked down after B. pseudomallei WT or ΔbipD infection." (PMID 38834545, 2024). "Interestingly, depletion of Cul3 in HEK293T cells did not alter infection with the HIV-1 ∆NF-κB/NFAT I, II mutant, suggesting that the NF-κB/NFAT binding sites in the LTR are crucial for the Cul3-mediated reduction of viral gene expression." (PMID 32882949, 2020).
neurodevelopmental disorder (6 papers, 2023 to 2025). A behavioral and cognitive disorder with onset during the developmental period that involves impaired or aberrant development of intellectual, motor, or social functions. "In this study, we identify a novel DNA methylation episignature as a sensitive diagnostic biomarker for NEDAUS, a neurodevelopmental disorder linked to CUL3 haploinsufficiency." (PMID 39501558, 2024). "CUL3 (Cullin-3 ubiquitin ligase; OMIM: 603136) haploinsufficiency is associated with a neurodevelopmental disorder (NDD) with or without autism or seizures (NEDAUS; OMIM: 619239)." (PMID 39501558, 2024).
psychiatric disorder (4 papers, 2016 to 2023). A disorder characterized by behavioral and/or psychological abnormalities, often accompanied by physical symptoms. "This suggests that CUL3 plays a significant role in early brain development and may also be implicated in postnatal psychiatric disorders." (PMID 37575562, 2023). "Interestingly, Cul3 has also been implicated as a causative gene in psychiatric disorders and has been shown to play an important role in Drosophila sleep." (PMID 32339168, 2020). "This indicates that CUL3 plays an important role in early brain development and may also be involved in postnatal psychiatric disorders." (PMID 37575562, 2023).
kidney disease (2 papers, 2019 to 2020). "Mutations in E3 ligases complex (e.g., KLH3 and CUL3 or VHL) lead to altered protein degradation by the UPS and subsequently to kidney disease." (PMID 33171965, 2020).
neurological diseases (2 papers, 2024 to 2025). "Our results link Inc-Cul3 complexes to sleep and synaptic function and provide tools to identify targets of Cul3, Inc, and Inc orthologs that impact normal brain function and neurological disorders." (PMID 39841692, 2025). "LZTR1 interacts with CUL3 and neurofibromin 1 (NF1) to regulate nighttime sleep by increasing GABA receptor signaling and has been associated with RAS-related neurological diseases caused by NF1 deficiency." (PMID 39062695, 2024). "Elucidating targets of Inc-Cul3 complexes within the fly brain may provide a powerful system to understand conserved mechanisms through which Cul3 and Inc contribute to nervous system function and neurological disorders." (PMID 39841692, 2025).
infectious disease (1 paper, 2024). A disorder directly resulting from the presence and activity of a microbial, viral, or parasitic agent in humans. "Although evidently not involved in regulation of infectious diseases, KLHL9/KLHL13/CUL3 E3 ligase complex was essential for BipD-dependent ubiquitination of mitochondria in mouse macrophages." (PMID 38834545, 2024).